ATP1A1-AS1 (ATP1A1 antisense RNA 1)
Synonyms: ATP1A1OS; C1orf203; MGC16179
Gene: Long non-coding RNA gene on chromosome 1 (116,378,437 to 116,421,301, reverse strand). Ensembl gene ENSG00000203865.
Gene Ontology:
Molecular function: U4 snRNA binding
Biological process: formation of quadruple SL/U4/U5/U6 snRNP; spliceosomal tri-snRNP complex assembly
Cellular component: U4/U6 x U5 tri-snRNP complex; U6 snRNP
Diseases named in the same sentence as ATP1A1-AS1 in open-access papers:
ATP1A1-AS1 is named in the same sentence as 1 disease in open-access papers, as found by Europe PMC text mining. Sharing a sentence is not in itself a finding about the gene and the disease.
ATP1A1-AS1 shares sentences with these, for which no sentence is quoted: cancer (1 paper).